MICA (MHC class I polypeptide-related sequence A)
Diseases named in the same sentence as MICA in open-access papers (continued):
Sharing a sentence is not in itself a finding about the gene and the disease.
tumor (continued). "In addition, NKG2D was found to play a significant role in tumor rejection and tumor immunosurveillance through binding to MICA/B, which are among the ligands binding to NKG2D receptors." (PMID 33440654, 2021). "MICA plays important roles in tumor surveillance and inflammation." (PMID 34208618, 2021). "In addition, tumor-secreted enzymes are able to shed the activating ligands B7-H6, MICA, MICB and ULBP2 from NK cells through the activity of metalloproteases." (PMID 33802954, 2021). "MICAB1 Fc-engineered mAb treatment also decreased the numbers of Raji-MICA*001 and MICA*008 tumor cells (exhibiting low and medium levels of surface MICA, respectively), recovered from the peritoneal cavity of NOD-SCID mice, relative to control mAb-treated mice." (PMID 35967081, 2021). "In addition, the involvement of MICA/B activation proteins was recently reported to impact on anti-tumor activity of NK cell." (PMID 34641520, 2021). "NKG2D is critical for tumor elimination and its down-regulation may arise as a consequence of the presence of soluble ligands such as MICA in plasma of cancer patients, a fact that contributes to tumor progression and immune escape." (PMID 34149719, 2021). "However, to evade NK cell recognition and to reduce the NKG2D-mediated NK cell activation, tumor cells shed MICA and MICB from their surface." (PMID 34203391, 2021). "Importantly, MICA/B expression was observed at the membrane of tumor cells, in addition to intracytoplasmic expression." (PMID 35967081, 2021). "However, MICA/B are frequently shed as an immune escape mechanism, preventing recognition and destruction of tumour cells by the immune system." (PMID 34897554, 2021). "Interestingly, it has been shown that patients with reduced MICA expression in tumor specimens have a significantly shorter disease-free and overall survival expectancy than patients with preserved MICA expression." (PMID 33266137, 2020). "MICA/B+ primary HCC cells isolated from tumor resections were used as target cells in a second set of experiments in which the anti-MICA/B mAb significantly increased PB NK degranulation activity for both allogeneic HCC primary cells in HD and autologous cells in the case of HCC patients." (PMID 33266137, 2020). "However, tumor cells also express molecules that activate NK cells, e.g., MHC class I polypeptide-related sequence A (MICA) and MICB, supporting the use of NK cells as anti-cancer agents." (PMID 32762681, 2020). "There is a significant inverse correlation of NODAL with MICA/B on the tumor cell surface." (PMID 32636849, 2020). "Additionally, the use of tumor hyperthermia as a tool in immunotherapy induced an upregulation of MICA, leading to an increase in the sensitivity of tumor cells to NK cell cytotoxicity." (PMID 32784928, 2020). "Such sMICA may differ in its effects on NKG2D modulation from tumor-released MICA, especially when embedded in exosomes." (PMID 32582150, 2020). "Previous studies found that the down-modulation of MICA/B on tumor cells could affect the outcome of the disease." (PMID 33266137, 2020). "The consequences of constitutive MICA expression are poorly understood since it may have dual roles on anti-tumor immunity." (PMID 32849657, 2020). "Treating cancer with HC and thus reducing MICA expression can result in tumor immune evasion." (PMID 32849657, 2020). "However, the contribution of the Vδ1 TCR activation by MICA-expressing tumor cells is difficult to evaluate, because MICA also serves as a high affinity ligand for NKG2D expressed on Vδ1 T cells." (PMID 32413966, 2020). "Thus, NODAL perhaps mediates tumor cell escape by somehow regulating expression of surface MICA, the exact mechanism of which remains to be determined." (PMID 32636849, 2020).
tumor (continued). "Though not statistically significant, MICA ∗019 had low association with tumor size and invasion depth of CRC (p = 0.064 and p = 0.096, respectively) as did MICA ∗008 to the distance metastasis and differential degree of CRC (p = 0.053 and p = 0.071, respectively)." (PMID 32528529, 2020). "In addition, human Vδ1 T cells can recognize MICA-expressing tumor cells by direct binding of MICA to Vδ1 TCR." (PMID 32413966, 2020). "Notably, EV isolated from MSC of HL patients and HL tumor cell lines treated with the specific ADAM10 inhibitors retain the ability to inhibit shedding of the ADAM10 substrates MICA, tumor necrosis factor (TNF)α and CD30 in recipient cells." (PMID 32668783, 2020). "Upon infection or in the presence of a tumor, the expression of MICA and MICB increased." (PMID 32010486, 2020). "It is also worth noting that modulation of MICA/B on HCC cells may represent a tumor escape mechanism." (PMID 33266137, 2020). "In this study, we report that platelet cloaking of tumour cells promotes the loss of the NKG2D ligands, MICA and MICB, from the surface of tumour cells, inducing their secretion into the tumour microenvironment where they suppress NKG2D receptor expression on NK cells." (PMID 30908480, 2019). "Each tumour cell line expressed varying levels of MICA and MICB ligand on unstimulated cells." (PMID 30908480, 2019). "The role of the MICA/B-NKG2D signal axis in tumor immune surveillance has been well documented." (PMID 31387641, 2019). "Hypoxic conditions downregulated MICA on the surface of tumor cells by different mechanisms, including shedding of this NKG2DL mediated by HIF1α-dependent upregulation of the matrix metalloproteinase A disintegrin and metalloproteinase domain-containing protein 10 (ADAM10)." (PMID 31535086, 2019). "By treating releasate from platelet cloaked tumour cells that contained platelet soluble factors plus tumour cell soluble factors, with neutralising antibodies to MICA and MICB the suppression of NKG2D, degranulation and pro-inflammatory cytokine production was partially rescued." (PMID 30908480, 2019). "Besides, soluble MICA released by tumor cells contributes to tumor immune evasion through down-regulating NKG2D and inactiving tumor-antigen-specific effector T cells." (PMID 32010612, 2019). "Future studies aimed to assess the anti-tumor activity of MICA specific antibodies may require complex mouse genetic engineering to incorporate a human transgene to minimize immunogenicity of human MIC proteins." (PMID 31387641, 2019). "Proteolytic shedding of MICA from tumor cells, might promote immunosubversion by reducing the expression of NKG2D." (PMID 32010612, 2019). "For example, in PC-3 prostate cancer cells, MICA is secreted by exosomes and exits the tumor cells." (PMID 30813924, 2019). "The potential activities of MICA-ICs were most pronounced when a tumor-free NK cell system was used, indicating that cancer cell co-cultures may further impede immune cell activity." (PMID 31387641, 2019). "In addition, the uptake of MICA-ICs by macrophages and dendritic cells within the tumor mass can potentially enhance the priming of anti-tumor immune responses, and amplify the therapeutic activities of anti-tumor agents." (PMID 31387641, 2019). "MICA protein is a ligand of the NK cell surface activating receptor, NKG2D, which can effectively mediate NK cell killing of tumor cells by binding activation proteins; however, many MICA-positive tumors release soluble MICA (sMICA) into the serum, which inhibits NK cell function." (PMID 31419949, 2019). "However, most γδ T cells also express the activating NKG2D receptor, which endows them with a TCR-independent second activation pathway via recognition of NKG2D ligands (e.g., MICA/B) on tumor cells." (PMID 29593742, 2018). "However, some proteases in the tumor microenvironment have been reported to shed the membrane-bound MICA, releasing soluble MICA into the bloodstream." (PMID 30463262, 2018).
tumor (continued). "CD8+NKG2D+ cells were generated from human peripheral blood and could be activated directly by their cognate ligands such as MICA/B often expressed on the surface of tumor cells." (PMID 29784005, 2018). "Interestingly, enhanced expression of MICA/B by oxidative stress on tumor cells has been correlated to an increased frequency of Vδ1+ T cells among tumor infiltrating lymphocytes (TIL)." (PMID 30298063, 2018). "Similarly, the use of antibodies against the α3 domain of MICA to decrease the release of ligand also promotes tumour immunity." (PMID 29720199, 2018). "Although the fusion protein MICA-Fas combining NK cell activation and apoptosis induction was powerful against tumor, a significant problem is the specific delivery of the fusion gene to tumor cells." (PMID 29316666, 2018). "One mechanism of hypoxia-mediated tumor evasion is MICA shedding." (PMID 29963058, 2018). "Interestingly, it was proven that IFN-γ can downregulate MICA expression via miRNA-520b, leading to the escape of tumor cells from immune surveillance." (PMID 30013574, 2018). "Moreover, GM6001 mostly inhibits the activity of secreted MMP-1, 2, 3, 7, 8, 9 and 12 and almost completely prevents the shedding of MICA/B at the surface of tumor cells treated with the CAFs CMs, suggesting that one or several of these MMPs are involved." (PMID 28423623, 2017). "Furthermore, we evaluated by ELISA the presence of soluble MICA (sMICA) or MICB (sMICB) in tumor cell supernatants following treatment with the CAFs CMs." (PMID 28423623, 2017). "Moreover, Cytochalasin D, nocodazole, and docetaxel can enhance NKG2D, DNAM-1, and NKp30 ligands on tumor cell surface, with MICA upregulation being dependent on both DNA damage and endoplasmic reticulum (ER) stress response." (PMID 28993779, 2017). "Interestingly, the same amount of shed MICA, purified from supernatant of tumor cells, inhibited NK cell cytotoxicity and infiltration to the same extent as a cocktail of sNKG2DLs." (PMID 28443091, 2017). "In another example, multiple tumor cells lines demonstrated their selection towards removal of MHC-I MICA and MICB ligands by packaging them into exosomes to avoid their recognition by the NKG2D activating receptor found on patrolling cytotoxic CD8 T cells and natural killer cells." (PMID 28806909, 2017). "Moreover, NKG2D receptor on NK cells binds to MICA, one of its ligands, on monocytes that reside in the tumor microenvironment, boosting NK cell antitumor activity against Ab-coated tumor cells and ultimately increasing their production of interferon-γ (IFNγ)." (PMID 29403144, 2017). "We next tested whether induction of MICA/B expression in tumor cells under genotoxic stress was due to ROS production." (PMID 27494876, 2016). "Therefore, in a future study it would be interesting to analyze MICA expression on tumor circulating cells from a range of MICA positive tumors and test if these cells lose MICA expression in vivo as a mechanism of immune evasion." (PMID 28154561, 2016). "Moreover, when ADAM 10 was overexpressed in these tumor cells, the 5-FU-induced the upregulation of MICA expression and downregulation of sMICA secretion were both attenuated." (PMID 27385218, 2016). "Besides downregulation of MHC I molecules, tumor cells can also present “induced-self” antigens including MHC class I-related sequence A (MICA) and MICB." (PMID 27843441, 2016). "Moreover, 5-FU increased and maintained membrane MICA (the ligand of NKG2D) expression on tumor cells through the inhibition of ADAM10." (PMID 27385218, 2016). "MICA shedding not only results in a reduction of MICA surface density on tumor cells but also generates sMICA, which was shown to systemically down-regulate NKG2D on cytotoxic effector cells and to promote expansion of immunosuppressive, intratumoral CD4+ NKG2D+ T cells." (PMID 27306684, 2016).
tumor (continued). "Furthermore, we identified the novel role of transcription factors GATA-2 and GATA-3 in suppressing MICA/B expression, which contributes to tumor escape from NK lysis." (PMID 27528231, 2016). "Therefore, the MICA staining of an in vivo tumor correlated with the in vitro findings in this study." (PMID 28154561, 2016). "Here, we could observe that MICA expression was higher on cells at the surface of the tumor than in the core." (PMID 28154561, 2016). "We thank Dr. Kenneth B. Ain (University of Kentucky Medical Center, KY) for kindly providing MRO87 tumor cell line, Dr. Veronika Groh (Fred Hutchinson Cancer Research Center, University of Washington, Seattle, WA) for kindly providing anti-MICA/B mAb (Clones 6D4), Ms." (PMID 27494876, 2016). "Thus, mAb04-MICA is a promising new approach for NK cell-based immunotherapy for malignancy and the strategy of treatment with MICA fused antibody can be further applied to other tumor specific markers such as Her2 and EGFR." (PMID 26909862, 2016). "It is well known that MICA and MICB, which are the ligands of NKG2D and expressed on tumor cells, are important molecules for stimulating the cytoxicity of immune cells, and MICA can easily fall off to soluble MICA (sMICA), which inhibits the activity of NK cells." (PMID 27385218, 2016). "In addition to those membrane-bound forms, MICA/B molecules are also cleaved proteolytically from tumor cells and appear as soluble forms in the sera of patients with malignancies." (PMID 27385218, 2016). "Thus, induction of mMICA expression by HDACi in HCC cells was confirmed to enhance NK cell cytotoxicity through MICA signaling, leading to the more efficient elimination of target tumor cells." (PMID 27910927, 2016). "Here, we could see that the surface of the tumor had a stronger MICA expression than at the core, recapitulating the in vitro results." (PMID 28154561, 2016). "The percentage of lysis by haNK cells at a 10:1 ratio of eight carcinoma cell lines was evaluated relative to the tumor cell lines’ expression of MHC class I chain-related protein A (MICA), PD-L1, and MHC class I, both in terms of percentage of cells expressing each marker and MFI." (PMID 27861156, 2016). "Furthermore, after 35 and 41 days from treatment beginning, 4 animals for each group were sacrificed for immunohistological analysis that revealed that SR141716 upregulated the expression of MICA in the tumor xenograft compared to the control group." (PMID 26008966, 2015). "In addition to the HER1/2 levels, we analyzed expression levels of surface markers CD9 and MICA on the mono-dispersed patient tumor cells." (PMID 26579120, 2015). "Although NVP-AUY922 activates HSF1, neither the MICA/B surface density on tumor cells nor their susceptibility to NK cell-mediated lysis was affected." (PMID 25854583, 2015). "Other ER residents such as ERp5/PDI6 (PDI family) are present on tumor cell surfaces; in this case, the chaperone is involved in the release of the NK cell activating receptor MICA from tumor cell surfaces, presumably as a protective measure to avoid NK attack." (PMID 25610811, 2014). "Consistently, statistically significant interaction was observed between tumor stage and rs9272143 (P = 4.4 × 10−4), but not between tumor stage and MICA alleles (all P > 0.05)." (PMID 24403192, 2014). "This raises the possibility that MICA/B may be specific targets on tumor cells for NK-mediated cytolytic activity." (PMID 25228093, 2014). "In addition, ADAM9 inhibition increases the expression of membrane-bound MICA on the tumor cell, enhancing the NK sensitivity of hepatocellular carcinoma cells." (PMID 24715892, 2014). "In addition, the combination of lenalidomide with GSK3 inhibition further enhanced MICA expression, which further supports the combined mechanistic benefit of these agents with current anti-tumor therapies." (PMID 24391651, 2013).
tumor (continued). "For example, HDAC inhibitors cause the upregulation of NKG2D ligands, MICA/B and ULBPs, in tumor cells but not healthy cells." (PMID 24391651, 2013). "Similarly, the downregulation of MHC class I-related chain A (MICA) expression impedes the detection of tumor cells by innate cytotoxic effector cells through the engagement of the NKG2D-activating receptor." (PMID 23763830, 2013). "In our experimental set up it seems however unlikely that the decrease in NKG2D expression could be explained through hypoxia induced MICA secretion by the tumor cells." (PMID 23724099, 2013). "Gefitinib could block the immune escape by up-regulating the expression of NKG2D ligands ULBP1, ULBP2 or MICA on tumor cells and NKG2D on NK cells in the co-culture system." (PMID 23937717, 2013). "By binding to NKG2D receptor, soluble MICA/B molecules may block the activation of effector lymph cells by MICA/B, thereby facilitate the escape of tumor or infected cells from immunosurveillance." (PMID 23181907, 2012). "In addition to their membrane-bound forms, MICA and MICB can be released from the surface of tumor and infected cells following proteolytic cleavages, yielding soluble MICA (sMICA) and MICB (sMICA) in serum." (PMID 23181907, 2012). "Our previous results indicated that a G allele of SNP rs2596542 was significantly associated with the lower cancer risk and the higher level of soluble MICA (sMICA) in the serum of HCV-induced HCC patients, demonstrating the possible role of MICA as a tumor suppressor." (PMID 23024757, 2012). "Thus, soluble MICA released from tumor cells by proteolytic cleavage drives down-regulation of NKG2D and is associated with compromised immune response and progression of disease in cancer patients." (PMID 22253598, 2012). "The expression and modulation of MICA on tumor cells have effects on cell survival." (PMID 21935360, 2011). "It seems that IL-10 is a significant element in the modulation of NKG2D ligand (MICA), decreasing its expression; therefore, this interleukine may prevent the tumor cytotoxicity mediated by the NKG2D/MICA axis." (PMID 24212778, 2011). "We further explored whether the surface expression level of MICA/B played any role in co-stimulation of one-tumor cells better than other by γδ T cells." (PMID 21935360, 2011). "The changes in pErk expression levels after exposure to γδ T cells may lead to differential regulation of MICA expressions, which might result in various levels in apoptosis in various tumor cells." (PMID 21935360, 2011). "NK-92 cells preferentially kill a panel of MICA/B-positive tumor cell lines." (PMID 21605422, 2011). "In this respect, IL-10 has been related to the regulation of MICA expression in tumor cells." (PMID 24212778, 2011). "Even though resistant tumor cells can escape immune recognition from γδ T cells by down regulating surface expression of MICA, γδ T cells can still be able to slow down the progression of the tumor cell proliferation by inhibiting cell cycle related molecules CDK2, CDK4 and Cyclin D1." (PMID 21935360, 2011). "It is likely that other NK activation receptors or other members of MICA/B such as ULBP1-4 and Letal, a recently identified NKG2D ligand, may also participate in NK-92 cell-mediated cytotoxic activity against MICA/B-negative tumor cell lines." (PMID 21605422, 2011). "However, MICA and MICB can be cleaved from tumor cells by tumor-associated mellatoproteinases, which leads to soluble MICA and MICB that can downregulate the expression of NKG2D." (PMID 20350313, 2010). "This suggests that metalloproteinases, aside from playing an important role in invasion, metastasis, and angiogenesis processes, may also have a role in allowing MICA shedding tumor cells to evade immune attack." (PMID 18208618, 2008). "However, transwell experiments demonstrated that direct contact between CD8+ T cells and MICA-expressing tumor cells caused NKG2D down-modulation, indicating that surface MICA was responsible for that defect." (PMID 18208618, 2008).